TIMP3 (TIMP metallopeptidase inhibitor 3)
Diseases named in the same sentence as TIMP3 in open-access papers (continued):
Sharing a sentence is not in itself a finding about the gene and the disease.
tumor (continued). "Gross and microscopic assessment of lung metastases indicated multiple lesions in PyMT Timp3+/+ tumor bearing 80-day-old mice, but these were completely absent in the PyMT Timp3−⁄− cohort." (PMID 25807548, 2015). "First, visualization of mammary wholemounts revealed multiple tumor foci in PyMT Timp3+/+ at day 40, which were absent in PyMT Timp3−⁄− glands." (PMID 25807548, 2015). "Interestingly, MMTV-PyMT Timp3−⁄− mice have delayed tumor onset and 36% of MMTV-Neu Timp3−⁄− mice remain tumor free." (PMID 25807548, 2015). "The tumor suppression in Timp3 null mice requires Tnfr1, but does not result in alterations in the local immune compartment." (PMID 25807548, 2015). "Using logistic regression, thereby allowing for the controlling of confounders (alcohol use, tumor size, lymph node status, and smoking), patients positive for HPV16 had increased hypermethylated CADM1 (OR = 19.3, CI = 7.5–49.3) or TIMP3 (OR = 5.9, CI = 2.3–15.6)." (PMID 25065733, 2014). "Furthermore EFEMP1 was found to strongly interact with other extracellular matrix (ECM) proteins such as TIMP3, and blocked the functional activity of VEGF, and inhibited tumor metastasis." (PMID 23840707, 2013). "In GBM, there is frequent hypermethylation of tumour suppressors (RB1, EMP3, RASSF1A and BLU), cell cycle regulators (p16INK4a and p15INK4b), DNA repair genes (MGMT, MLH1), and genes involved in tumour invasion and apoptosis (DAPK, TIMP3 and CDH1)." (PMID 22771539, 2013). "The quantitative DNA methylation analysis of the candidate genes showed higher methylation proportion in the primary tumor tissue than that of the matched normal tissue and the differences were significant for the APC, BIN1, BMP6, BRCA1, CST6, ESR-b, P16, PTEN and TIMP3 promoter regions (P<0.05)." (PMID 22695536, 2012). "Methylated TIMP3 revealed significant correlation to the primary tumor tissue lacking expression of PR (Spearman's rho test; P < 0.05)." (PMID 22695536, 2012). "Timp3, or tissue inhibitor of metalloproteinases-3, has been found to inhibit angiogenesis through a VEGF mediated pathway, and has been found to be silenced through promoter hypermethylation in a variety of tumor types." (PMID 20520817, 2010). "Methylation of P16(INK4A), MLH1, TIMP3 and DAPK in normal mucosa occurred at a lower level than ERα and MYOD but also increased with age and was significantly higher in patients with CIMP+ tumours." (PMID 16421593, 2006). "The expression of TIMP3 and TIMP4 decreased progressively with increasing Gleason score, supporting the classic notion that these inhibitors may be protective in tumour progression." (PMID 15928670, 2005). "Multivariate analysis showed that TIMP-3 overexpression was not a prognostic factor by itself, in contrast to depth of tumour invasion, lymph node metastasis, or disease stage (data not shown)." (PMID 15467768, 2004). "Likewise, miR-21 confers resistance by suppressing tumor suppressors including PTEN and tissue inhibitor of metalloproteinase 3 (TIMP3), thereby attenuating apoptosis and promoting survival under therapeutic stress; functional rescue experiments here also support a causal role." (PMID 41425255, 2025). "Also, exosomal miR-21 regulates the invasion and metastasis of tumors by targeting multiple tumor/metastasis suppressor genes in recipient cells, while miR-221/222 promotes angiogenesis in recipient endothelial cells by downregulating c-KIT, p27, and TIMP3." (PMID 39409003, 2024). "The classifiers have determined that patients with benign prostate biopsies before the diagnosis of PCa showed a high MMPs/TIMP-3 expression by ECs, so in the zone without future cancer development as in the zone with future tumor, compared with biopsy samples from patients with BPH or HGPIN." (PMID 37108185, 2023). "However, our study is still limited by the lack of tumor specimens and information on TIMP3 expression levels from patients with prostate cancer." (PMID 36612628, 2022).
tumor (continued). "Finally, TIMP3 (TIMP metallopeptidase inhibitor 3) over-expression, by the retroviral vector delivery to NXS2 NB cells, had anti-proliferative effects on the growth of tumor cells after s.c. injection to mice." (PMID 36231134, 2022). "Decorin also inhibits tumor cell-mediated production of hypoxia-inducible factor-1α (HIF-1α), and c-Met, and concurrently stimulates the rapid production of the antiangiogenic, angiostatic molecules thrombospondin-1 and tissue inhibitor of metalloproteinases 3 (TIMP3)." (PMID 32489466, 2020). "Although MPT0B390 strongly induced TIMP3 mRNA and protein expression, as well as apoptosis activation in HCT116 cells, our findings show that it did not inhibit tumor cell survival through TIMP3 induction according to the same viability in siRNA-mediated blockage of TIMP3 upregulation." (PMID 31588243, 2019). "Moreover, DCN inhibits hypoxia inducible factor-1α (HIF-1α) and VEGFA via a Met-dependent pathway and induction of the endogenous angiostatin proteins thrombospordin-1 and tissue inhibitor of metallo-proteinases-3 (TIMP3) to promote anti-angiogenesis and prevention of tumour growth and metastasis." (PMID 29435195, 2018). "miR-21, in turn, suppresses the expression of tumor suppressors such as phosphatase and tensin homolog (PTEN), programmed cell death protein 4 (PDCD4), reversion-inducing-cysteine-rich protein with kazal motifs (RECK), and metalloproteinase inhibitor 3 (TIMP3) by direct targeting." (PMID 29538313, 2018). "Importantly, KDM1A exerts these effects by epigenetically silencing TIMP3 transcription, which in turn increases MMP2 expression in the extracellular matrix (ECM) and JNK phosphorylation in the cytoplasm of tumor cells, thus contributing to cell invasion and migration in NSCLC." (PMID 27058897, 2016). "Moreover, MPT0G013 significantly induced TIMP3 mRNA and protein expression in endothelial cells and tumor xenografts, and whereas SAHA had a similar pattern of inhibitory activities on HDAC subtypes, it barely induced TIMP3 gene or protein expression in vitro or in vivo." (PMID 25226613, 2014). "Moreover, recent studies in mice lacking TIMP3, further extend the role of TIMP3 as a tumor suppressor and emphasize TIMP3 as a candidate for therapeutic use in cancer." (PMID 23894681, 2013). "In the tumor microenvironment, an imbalance may arise from an increase in MMP expression/activity and a decrease in the expression of the MT-MMP inhibitors, TIMP-2 or TIMP-3." (PMID 21349159, 2011). "In addition, group 2 showed a significantly higher percentage of tumours positive for TIMP-1, MMP-9 and -11 in the tumour cells; as well as a significantly higher percentage of tumours positive for TIMP-2, TIMP-3, MMP-9, -11, -13 and -14, in fibroblastic cells." (PMID 17848954, 2007). "Five genes, ROBO4, SNRK, TM4SF1, FMO2 and TIMP3, found in this screen have been preferentially associated with capillary endothelial cells from mouse lung and TMBM expression was found specifically in tumour endothelial cells, but not normal endothelial cells." (PMID 16390543, 2006). "Specifically, both groups of authors used polymerase chain reaction to assess TIMP-3 mRNA expression levels in tumor tissue, without distinguishing whether mRNA comes from the malignant cells or the surrounding stromal cells." (PMID 17032447, 2006). "Thus, we argue that the proportion of stromal cells in the prostate tissue homogenates does not vary appreciably between benign and malignant tissues, and therefore the reduced expression of TIMP3, TIMP4 and RECK is most likely a functional consequence of tumour–stromal interactions." (PMID 15928670, 2005). "Therefore, TIMP-3 may suppress tumour angiogenesis indirectly by inhibiting the VEGF angiogenesis signal, and in turn, tumour growth." (PMID 15467768, 2004). "By RT-PCR, TIMP-2 and TIMP-3 expression did not change with tumour grade." (PMID 11437402, 2001). "The lack of TIMP3 may enhance the invasion ability of poorly differentiated tumours." (PMID 38542164, 2024).
tumor (continued). "Furthermore, the TIMP-3 SNP rs9619311 variant may lead to higher tumor stage of UCC in the non-smoker population, which is in accordance with the oncogenic effect of TIMP-3 for UCC according to the result of TCGA analysis." (PMID 36860920, 2023). "In addition, the decrease of circCSNK1G3 also facilitated the expression of TIMP3, a member of tissue inhibitors of metalloproteinases (TIMP) family, which regulate a vast range of cell surface proteins and resulting in prominently effects on tumour growth and cancer metastasis." (PMID 33560588, 2022). "Another hypothesis suggests that EGCG induces the expression of TIMP-3, a gene that negatively regulates matrix metalloproteinases, in both MDA-MB-231 and MCF-7 cell lines, thus culminating in the inactivation of metalloproteinases and containing tumor invasion." (PMID 34945706, 2021). "It was also of note that our finding indicated that ECs from the non-tumor zone from prostatectomy specimens (C3) showed higher expressions of MMP-9 -11, and TIMP-3 than ECs from the zone without future cancer development from biopsy (C1)." (PMID 37108185, 2023). "Other genes were down-regulated in tumour versus adjacent tissue, most prominently CXCL12 (20.6-fold in patients without DMI and 21.7-fold in patients without LVI), followed by TIMP3 (15.0-fold in DMI absent and 16.2-fold in LVI-absent EC)." (PMID 37509322, 2023). "Expression levels of TIMP3 were similar between DEN-induced miR-181 KO and WT tumours in mice (data not shown)." (PMID 35867177, 2022). "TIMP3 gene decreased in CRC patients compared to controls and slightly increased in tumor tissues compared to adjacent none-tumor tissues." (PMID 32171282, 2020). "A correlation study of the methylation proportion of DNA in serum versus cancerous and normal breast tissue revealed a correlation between tumor tissue and serum for BMP6, BRCA1, CST6, GSTP1, P16 and TIMP3 genes but not with the matched normal tissue." (PMID 21283676, 2011). "Nevertheless, fibroblasts from tumor areas (C4) show higher expression of MMP-2 and TIMP-3, compared with fibroblasts from non-tumor areas from prostatectomies (C3), which indicate that more pronounced dramatic changes occur in the most intimate tumor microenvironment." (PMID 37108185, 2023). "While the methylation data for RASSF1α from TCGA correlated with the DNA methylation levels in saliva collected from HPV-positive HNSCC patients, the overall methylation status of TIMP3 and PCQAP did not vary significantly in tumour samples compared to salivary DNA methylation levels." (PMID 27663357, 2016).
cancer (198 papers, 1997 to 2026). A tumor composed of atypical neoplastic, often pleomorphic cells that invade other tissues. "The overexpression of TIMP1 or downregulation of TIMP3 is linked to cancer progression and poor prognosis in patients." (PMID 40244296, 2025). "In MCF-7 and MDA-MB-231 cancer cell lines, the induction of the tissue inhibitor of metalloproteinases-3 (TIMP-3) mRNA was associated with EGCG and GTP." (PMID 39407505, 2024). "Downregulation of TIMP3 is associated with cancer progression and poor prognosis and TIMP3 silencing has been found in multiple human cancers." (PMID 37313172, 2023). "Among the members of the family, TIMP3 silencing is usually associated with cancer progression or poor patient prognosis, but some studies also reported poor prognosis associated with high TIMP3 expression." (PMID 37511403, 2023). "From this, it can be seen that the TIMP3 rs9619311 also plays an important role in prostate cancer, and patients with the “TC + CC” polymorphic variant are at high risk for both cancer progression and biochemical recurrence." (PMID 36612628, 2022). "Single nucleotide polymorphisms (SNPs) of tissue inhibitor of metalloproteinases-3 (TIMP-3) have been revealed to be related to various cancers." (PMID 35813301, 2022). "Based on the TCGA-LUAD cohort, patients with high percentage of cancer associated fibroblasts and TIMP3 expressions were associated with resistance to immunotherapy." (PMID 35480306, 2022). "The rs9619311 polymorphism in the promoter region of TIMP3 and other two polymorphisms (rs9862 and rs11547635) have been reported to play a role in the risk of various cancers." (PMID 36612628, 2022). "Multiple studies have reported that the T allele of TIMP3 rs9862 is associated with a higher risk of developing cancer and decreased survival." (PMID 36612628, 2022). "Patients with high percentage of cancer associated fibroblasts and expression of TIMP3 but low expression of COL1A1, COL3A1, MMP1 and POSTN were associated with sensitivity to paclitaxel." (PMID 35480306, 2022). "As a key component of proteolytic activity regulation, TIMP3 was found to be associated with cancer progression and poor patient prognosis." (PMID 34599146, 2021). "Meanwhile, TIMP3, which encodes a metalloproteinases inhibitor, also suppresses the invasion and migration of a few cancer types such as LIHC and THCA." (PMID 33766047, 2021). "Several studies have shown that that high levels of TIMP-3 mRNA are associated with a good prognosis in different types of cancer." (PMID 33419373, 2020). "The network revealed that CRC-related DERs such as hsa-miR-1-3p, hsa-miR-490-3p, hsa-miR-542-5p, hsa-miR-424-5p, and hsa-miR-133a-3p are associated with the regulation of several cancer-related pathways by targeting TIMP3, FOS, PPP1R12B, CCND2, and EGFR." (PMID 32153636, 2020). "Tissue inhibitor of metalloproteinases-3 (TIMP3) is associated with the acceleration of cancer invasiveness and the development of metastasis." (PMID 31817446, 2019). "The overexpression of TIMP3 has both promoted the transformed phenotype and caused cell death of cancer cell lines." (PMID 25807548, 2015). "Conclusively, we believe that TIMP-3 significantly exerts anti-oncogenic roles and that positive TIMP-3 expression critically suspends malignant activities associated with cancer invasion." (PMID 25171061, 2014). "TIMP3 methylation has been associated with cancer outcomes and response to treatment in a number of studies." (PMID 23527119, 2013). "TIMP3 has a high frequency of genetic variation in many types of human malignant tumors, including mutations, deletions, methylation, chromosomal translocation, and so on." (PMID 23819566, 2013). "This study, for the first time, presents CCNA1 and TIMP3 hypermethylation as a helpful tool to identify HNSCC subjects at risk of developing second primary carcinomas." (PMID 24359512, 2013).
cancer (continued). "As regards survival rate, decreased expression of TIMP-3 within the cytoplasm of cancer cells was associated with poor disease-free survival of our patients." (PMID 17032447, 2006). "The database queried for TIMP3 gene mutations in 2850 samples from 10 cancer studies of CRC." (PMID 41009435, 2025). "The prevalence of mutations in oncogenic drivers is greater in TIMP3-low cancers." (PMID 41009435, 2025). "In this research, we verified that the expression of TIMP3 was significantly down-regulated in LC tissues compared with the normal tissues, which is identical to the theory that the silencing of TIMP3 is consistently associated with cancer progression or poor patient prognosis." (PMID 38495494, 2024). "The loss of TIMP3 correlated with advanced-stage disease and poor prognosis in various cancers." (PMID 37509322, 2023). "One of the genes with the most reduced expression in both menopausal status subgroups was tissue inhibitor of metalloproteinases, TIMP3, the silencing of which is consistently associated with cancer progression or poor patient prognosis in multiple human cancers, including EC." (PMID 37509322, 2023). "Loss of TIMP-3 expression in cancer cells could lead to an increase of metalloprotease activity and therefore to their increased metastatic potential." (PMID 35207132, 2022). "TIMP-3 is downregulated in several human cancers, and its loss correlates with worse prognoses." (PMID 35207132, 2022). "These genetic polymorphisms may influence TIMP-3 expressions and have been demonstrated to be associated with susceptibility and progression of several cancers 20, 21, 36-38." (PMID 35813301, 2022). "In addition, TIMP1 overexpression or TIMP3 silencing have been linked to cancer progression and poor prognosis in NSCLC." (PMID 35688943, 2022). "In addition, TIMP-3 loss promotes cancer progression by reducing cell adhesion and increasing beta-catenin signaling." (PMID 35207132, 2022). "Therefore, we investigated increasing the sample size and the three TIMP3 genetic polymorphisms that are known to be strongly associated with cancer for further analysis." (PMID 36612628, 2022). "These functions all underlie TIMP3 as an inhibitor in various cancers, including GBM." (PMID 34781885, 2021). "In mRNA expression research, contradict with it in other cancers 25, we found over-expressed TIMP3 associated with worse OS, which means this phenomenon may cause by accelerating the aggressive behavior." (PMID 34093812, 2021). "Loss or down regulation of TIMP3 could promote the metastasis, cell growth and invasion of several cancers." (PMID 33750388, 2021). "Actually, TIMP-3 was reported to be a biomarker associated with TKI resistance in cancer cells." (PMID 33126605, 2020). "TIMP-3 downregulation is related to cancer invasion and metastasis in various cancers; however, higher serum level of TIMP-1 is associated with lower response to therapy in breast cancer patients, and TIMP-1 has been used as a biomarker along with MMP-2 and ICAM-1 for pancreatic cancer." (PMID 32466129, 2020). "High TIMP3 expression associated with TC and CC genotypes coupled with the cancer protective function of estrogen may be responsible for the observed decreased CRC risk in females of our population when studied with respect to TIMP3-1296T/C SNP." (PMID 30988064, 2019). "As previously shown for other types of cancer-associated fibroblasts, treatment by luteolin could reverse this fibroblast phenotype and decrease TIMP3 secretion." (PMID 31671543, 2019). "TIMP3 exhibits anti-cancer actions via the inhibition of metalloproteinases, including several ADAMs, which has been shown to block cell migration and invasion associated with cancer cell metastasis." (PMID 30214383, 2018).